RMI2 (RecQ mediated genome instability 2)
Description:
Essential component of the RMI complex, a complex that plays an important role in the processing of homologous recombination intermediates. It is required to regulate sister chromatid segregation and to limit DNA crossover. Essential for the stability, localization, and function of BLM, TOP3A, and complexes containing BLM. In the RMI complex, it is required to target BLM to chromatin and stress-induced nuclear foci and mitotic phosphorylation of BLM.
Synonyms: BLAP18; C16orf75; MGC24665
Tractability: Small molecule: a structure with a bound ligand is known. PROTAC: ubiquitination databases record sites on it.
Gene: Protein-coding gene on chromosome 16 (11,249,619 to 11,381,662, forward strand). Ensembl gene ENSG00000175643.
Subcellular location: Nucleus
Subcellular location (Human Protein Atlas): Nuclear speckles; Cytosol
Pathways (Reactome):
DNA Repair: HDR through Homologous Recombination (HRR); HDR through Single Strand Annealing (SSA); Homologous DNA Pairing and Strand Exchange; Presynaptic phase of homologous DNA pairing and strand exchange; Processing of DNA double-strand break ends; Resolution of D-loop Structures through Holliday Junction Intermediates; Resolution of D-loop Structures through Synthesis-Dependent Strand Annealing (SDSA)
Disease: Defective HDR through Homologous Recombination Repair (HRR) due to PALB2 loss of BRCA1 binding function; Defective HDR through Homologous Recombination Repair (HRR) due to PALB2 loss of BRCA2/RAD51/RAD51C binding function; Defective homologous recombination repair (HRR) due to BRCA1 loss of function; Impaired BRCA2 binding to PALB2; Impaired BRCA2 binding to RAD51
Cell Cycle: G2/M DNA damage checkpoint
Gene Ontology:
Molecular function: protein binding
Biological process: double-strand break repair via homologous recombination; regulation of sister chromatid segregation; resolution of DNA recombination intermediates
Cellular component: nuclear speck; RecQ family helicase-topoisomerase III complex; nucleoplasm; nucleus
Genetic constraint (gnomAD): Loss-of-function variants: 12 observed, 7.48 expected, observed/expected ratio (o/e) 1.61, 90% interval 0.98 to 1.94. That is too few expected variants to judge how well the gene tolerates losing a copy. Missense variants: 253 observed, 165.56 expected, observed/expected ratio (o/e) 1.53, 90% interval 1.38 to 1.7. Synonymous variants: 105 observed, 65.72 expected, observed/expected ratio (o/e) 1.6, 90% interval 1.36 to 1.86.
Homologues: Orthologues: chimpanzee RMI2 (100% identical), macaque RMI2 (98% identical), pig RMI2 (90% identical), rabbit RMI2 (87% identical), rat Rmi2 (86% identical), dog RMI2 (85% identical), guinea pig RMI2 (85% identical), mouse Rmi2 (84% identical), zebrafish rmi2 (47% identical), tropical clawed frog rmi2 (46% identical).
Diseases named in the same sentence as RMI2 in open-access papers:
RMI2 is named in the same sentence as 28 diseases in open-access papers, as found by Europe PMC text mining. Sharing a sentence is not in itself a finding about the gene and the disease. The quoted sentences say what the papers report.
Bloom syndrome (8 papers, 2016 to 2025). Bloom syndrome (BSyn) is a rare chromosomal breakage syndrome characterized by a marked genetic instability associated with pre- and postnatal growth retardation, facial sun-sensitive telangiectatic erythema, increased susceptibility to infections, and predisposition to cancer. "Mutations on BLM and the TRR (TOP3A/RMI1/RMI2) subcomplex have been linked to Bloom syndrome (BS) or BS-like genetic disorders, predisposing individuals to cancer development." (PMID 40846865, 2025). "The mutation of RMI2 is associated with Bloom syndrome, a recessive human genetic disease with features of and predisposition to cancer." (PMID 33083148, 2020). "Notably, this trans-eSNP was a cis-eQTL for RMI2, a gene associated with genome instability and Bloom syndrome." (PMID 36424644, 2022). "Overall, loss of RMI2 produces a partially active BLM complex with mild features of Bloom syndrome." (PMID 27977684, 2016). "Here, we show a homozygous deletion of RMI2 in two siblings with milder clinical features of Bloom syndrome." (PMID 27977684, 2016). "Bloom DNA helicase (BLM) combines closely with DNA topoisomerase IIIα (Top3A), RecQ-mediated genome instability protein 1 (RMI1), and RecQ-mediated genome instability protein 2 (RMI2) to form a conserved Bloom syndrome (BS) complex, which is vital for maintaining genome stability." (PMID 38007566, 2023). "Interestingly, the recruitment of FANCM requires its direct interaction with Bloom syndrome complex composed of BLM helicase, Topoisomerase 3α, RMI1 and RMI2; as well as the helicase activity of BLM." (PMID 28058110, 2016). "Therefore, it is suggested that individuals in the Bloom syndrome registry lacking molecular diagnosis may have causative variants in other genes as RMI1, RMI2, or TOP3A genes with the overlapping phenotypic manifestation." (PMID 37052241, 2023).
lung carcinoma (4 papers, 2021 to 2023). "Overexpression of RMI2 accelerated the growth and metastasis of lung cancer and was associated with poor outcomes." (PMID 36533385, 2023). "Several studies have shown the upregulated expression of RMI2, which is caused tumor progression in cervical cancer, lung cancer, and prostate cancer." (PMID 36251702, 2022). "High expression of RMI2 was confirmed to be associated with the worse prognosis in pancreatic cancer and lung cancer." (PMID 34408776, 2021). "Recently, a study related RMI2 expression to worse prognosis of lung cancer." (PMID 37875822, 2023).
breast carcinoma (3 papers, 2021 to 2023). "This is the first study to explore the associations of RMI2 with the proliferation and migration of breast cancer cells, as well as the PI3K/AKT signaling pathway." (PMID 36533385, 2023). "RMI2 is also upregulated in breast cancer and SNPs in BLM and RMI1 were associated with breast carcinoma." (PMID 33662042, 2021). "The results suggest that RMI2 is a potential diagnostic and prognostic biomarker associated with cell proliferation and migration, and may be used as a novel therapeutic target for breast cancer in the future." (PMID 36533385, 2023). "Consistent with the results of the bioinformatics database, RMI2 protein levels were increased in breast cancer tissues." (PMID 36533385, 2023). "This study on RMI2 expression in breast cancer had the largest sample size of any related study by far." (PMID 36533385, 2023). "Subsequently, the mRNA and protein levels of RMI2 in different breast cancer cell lines were investigated." (PMID 36533385, 2023). "The pooled SMD of RMI2 was 1.29 (95% CI: 1.18–1.41, p = 0.000), which indicated that RMI2 expression was significantly upregulated in breast cancer tissues compared to normal tissues." (PMID 36533385, 2023). "Results suggested that breast cancer patients with higher expression of RMI2 had shorter OS, DFS, and DMFS." (PMID 36533385, 2023). "There were significant differences in the expression of RMI2 among different subtypes of breast cancer, and the expression of RMI2 was relatively higher in the basal‐like and luminal B types based on the TCGA database." (PMID 36533385, 2023). "In the KEGG analysis of RMI2, it was found to be related to multiple cancer‐related signaling pathways in breast cancer, such as PI3K/AKT, Hedgehog, and MAPK signaling pathways." (PMID 36533385, 2023). "This study evaluates the differential expression, prognostic value, molecular functions, and related mechanisms of RMI2 in breast cancer." (PMID 36533385, 2023). "This study aims to evaluate the aberrant expression, molecular functions, prognostic value, and related mechanisms of RMI2 in breast cancer, and to provide a fundamental for molecular diagnosis and clinical therapy of breast cancer." (PMID 36533385, 2023). "knockdown of RMI2 remarkably inhibited the proliferation and migration of breast cancer cells, while overexpression of RMI2 exerted the opposite effects." (PMID 36533385, 2023). "The expression of RMI2 was markedly upregulated in breast cancer tissues relative to that in normal tissues." (PMID 36533385, 2023). "In summary, our study suggested that RMI2 is markedly upregulated in breast cancer and its high expression is correlated with poor prognosis." (PMID 36533385, 2023). "Subsequently, the expression pattern of RMI2 in breast cancer and normal tissues was further explored." (PMID 36533385, 2023). "Furthermore, we identified that RMI2 accelerates the proliferation and migration of breast cancer cells via activation of the PI3K/AKT pathway." (PMID 36533385, 2023). "Results revealed that RMI2 was markedly overexpressed in breast cancer tissues." (PMID 36533385, 2023). "In addition, in vitro assays demonstrated that RMI2 accelerates the proliferation and migration of breast cancer cells by activating the PI3K/AKT pathway." (PMID 36533385, 2023). "Subsequently, LY294002 (a PI3K inhibitor) was used to explore whether RMI2 mediated breast cancer progression through PI3K/AKT pathway." (PMID 36533385, 2023). "Finally, the functional mechanism of RMI2 affecting the progression of breast cancer needs further exploration." (PMID 36533385, 2023). "In addition, based on the median value of RMI2 expression, breast cancer samples from TCGA were divided into high and low RMI2 expression groups." (PMID 36533385, 2023). "Moreover, pooled SMD further confirmed the overexpression of RMI2 in breast cancer (SMD = 1.29, 95% confidence interval (CI): 1.18–1.41, p = 0.000)." (PMID 36533385, 2023).
breast carcinoma (continued). "The expression of RMI2 and its prognostic value in breast cancer was explored." (PMID 36533385, 2023). "Because of the limited reports, the role of RMI2 in breast cancer remains unclear." (PMID 36533385, 2023). "Subsequently, we explored whether RMI2 affected malignant phenotypes of breast cancer." (PMID 36533385, 2023). "Moreover, we combined 11 datasets to analyze the expression of RMI2 in breast cancer." (PMID 36533385, 2023). "Because of the limited number of reports, the function of RMI2 in breast cancer remains unclear." (PMID 36533385, 2023). "However, the functional mechanism of RMI2 in breast cancer remains unclear." (PMID 36533385, 2023).
Fanconi anemia (3 papers, 2021 to 2025). Fanconi anemia (FA) is a hereditary DNA repair disorder characterized by progressive pancytopenia with bone marrow failure, variable congenital malformations and predisposition to develop hematological or solid tumors. "For example, in the Fanconi Anemia pathway, RMI2 and FANCA demonstrated resistance patterns in 13 patients." (PMID 40294066, 2025). "Notably, upregulation of USP1, RMI2, and FANCE in the 2x load group, associated with the Fanconi anemia pathway, was observed among DNA repair‐related genes." (PMID 40080399, 2025).
hepatocellular carcinoma (3 papers, 2022 to 2023). A malignant tumor that arises from hepatocytes. "Survival analysis showed that high RMI2 expression was associated with poor prognosis of hepatocellular carcinoma (P=0.001)." (PMID 35552266, 2022). "We found alterations (amplification and mRNA expression levels) of RMI2 in 6% (24/373) of the hepatic carcinomas analyzed." (PMID 37875822, 2023). "RMI2 was overexpressed in hepatoma tissue and cell lines, and it promoted the migration and invasion of HCC cells." (PMID 37875822, 2023). "First, expression analysis showed that RMI2 was up-regulated in hepatocellular carcinoma (P<0.001)." (PMID 35552266, 2022).
neuropathy (3 papers, 2024 to 2025). A disorder affecting the nervous system that manifests with pain, tingling, numbness, and/or muscle weakness. "The rs2032930/rs2032931 are intronic SNPs found in the RMI2 (recQ-mediated genome instability protein 2) gene, and appeared to increase the risk of developing neuropathy." (PMID 38928135, 2024). "rs2032930/rs2032931 are intronic SNPs found in the RMI2 (recQ-mediated genome instability protein 2) gene and appeared to increase the risk of developing neuropathy." (PMID 38339094, 2024). "At this time, rs604349 in MYBPHL and rs2032930/rs2032931 in the RMI2 gene appear to be of importance in increasing the risk for developing neuropathy, while rs917778 in MVB12B and rs2234753 in the RXRA gene might reduce the likelihood of this complication." (PMID 38928135, 2024). "In the literature, we found no clue to an existing relationship between the RMI2 gene and developing neuropathy." (PMID 38339094, 2024).
prostate carcinoma (3 papers, 2020 to 2023). A carcinoma that arises from epithelial cells of the prostate gland. "A transcriptional role for MYCN in upregulating the DDR has been given further credence by the recent identification of MYCN binding sites in the promoters of PARP1, PARP2, BRCA1, RMI2, and TOPBP1, albeit in castration resistant prostate cancer." (PMID 32577161, 2020).
cervical squamous cell carcinoma (2 papers, 2023). A squamous cell carcinoma arising from the cervical epithelium. "RMI2 was identified as significant cervical squamous cell carcinoma after expression validation and survival analysis." (PMID 37875822, 2023).
lymph node metastasis (2 papers, 2023). "The expression of RMI2 was elevated in the lymph node metastasis group." (PMID 36533385, 2023).
anemia (1 paper, 2024). A reduction in the number of red blood cells, the amount of hemoglobin, and/or the volume of packed red blood cells. "Additionally, we found a clique that consists of Fanconi anemia (FA) proteins (FANCF, FANCM, FANCG and FANCD2) and a third clique with two FA proteins together with BLM and RMI2." (PMID 38909016, 2024).
autoimmune disease (1 paper, 2022). A disorder resulting from loss of function or tissue destruction of an organ or multiple organs, arising from humoral or cellular immune responses of the individual to their own tissue constituents. "In STAD, the pathways enriched in the high RMI2 expression group may be related to autoimmune diseases, while the pathways enriched in the low RMI2 expression group are mainly related to neurotrophic and olfactory pathways." (PMID 35552266, 2022).
diabetic neuropathy (1 paper, 2024). A chronic, pathological complication associated with diabetes mellitus, where nerve damages are incurred due to diabetic microvascular injury involving small blood vessels that supply these nerves, resulting in peripheral and/or autonomic nerve dysfunction. "We successfully identified three genetic variants (rs2032930 and rs2032931 of the RMI2 gene and rs604349 of the MYBPHL gene) which were associated with a 22–49-fold increase in the risk of developing diabetic neuropathy." (PMID 38339094, 2024).
leukemia (1 paper, 2022). A malignant (clonal) hematologic disorder, involving hematopoietic stem cells and characterized by the presence of primitive or atypical myeloid or lymphoid cells in the bone marrow and the blood. "High expression of RMI2 was correlated with 10 cancers (bladder, breast, cervical, colorectal, head and neck, liver, lung, lymphoma, ovarian, pancreatic) and significantly lower expression only in leukemia." (PMID 35552266, 2022).
multiple sclerosis (1 paper, 2022). A progressive autoimmune disorder affecting the central nervous system resulting in demyelination. "The last two genes, CLEC16A and RMI2, were also associated with CD, IBD, multiple sclerosis, and type I diabetes mellitus." (PMID 35464478, 2022).
prostate adenocarcinoma (1 paper, 2021). "Compared with normal samples, EXO1, RMI2, and RAD51 were significantly overexpressed in most cancer types including BRCA, while RMI2 was significantly lower expressed in PARD (Prostate adenocarcinoma)." (PMID 34408776, 2021).
tumor (8 papers, 2020 to 2023). "We also evaluated 72 pairs resected samples, results revealed that upregulation of CKS2 and RMI2 in lung ACA were associated with larger tumor size." (PMID 33083148, 2020). "Finally, the exact mechanism by which RMI2 occurs to tumor-associated immunity is still unclear." (PMID 35552266, 2022). "Results showed that when compared with normal tissues, RMI2 mRNA was highly expressed in multiple tumor tissues." (PMID 36533385, 2023). "Analysis of TILs confirmed that RMI2 expression was intertwined and entangled with the level of immune infiltration in different tumor types." (PMID 35552266, 2022). "To reflect the deaths identified as tumor factors during follow-up, we analyzed the relationship between RMI2 expression and DSS in TCGA 33 cancers." (PMID 35552266, 2022). "The high expression lever of RMI2 is related to many tumor types, and the poor prognosis and disease progression of tumors are related to its expression, especially in LIHC, PAAD." (PMID 35552266, 2022). "Overall, Usually, patients with late clinical-stage of tumor have poorer survival prognosis We analyzed the relevance between the expression of RMI2 and clinicopathological stage." (PMID 35552266, 2022). "RMI2 was also reported to act as a tumor promoter by mediating MYCN/PARP DDR signaling pathway in neuroendocrine prostate cancer." (PMID 34408776, 2021). "We further validated CKS2 and RMI2 using clinical biopsy samples and demonstrated that higher expression of these two genes correlates with larger tumor size and poor clinical outcomes." (PMID 33083148, 2020). "There are 109 co-DEGs between the GSE75037 and GSE32863 datasets, and CKS2 and RMI2 had the relative high degrees at 32 and 23, manifesting that these two genes act a pivotal part in the genesis and progression of tumor." (PMID 33083148, 2020). "Next, we examined RMI2 expression in the tumor samples with western blotting." (PMID 37875822, 2023). "Different immune infiltrating cells are complex and changeable in the occurrence and development of tumors, so for different tumors, the study of the relationship between RMI2 and immune infiltration-related cells can promote tumor immunity and drug development and therapy." (PMID 35552266, 2022). "In combination, we found that RMI2 was significantly overexpressed in 22 tumor types." (PMID 35552266, 2022). "Compared with other genes, MCM2, TOP2A, CDC45, KNTC1, RFC4 and RMI2 were highly expressed in CESC tumor tissues and might be better indicators of prognosis." (PMID 34174849, 2021). "Results revealed both the CKS2 and RMI2 are higher expressed in tumor than normal lung tissues." (PMID 33083148, 2020). "And also we explored the correlation of RMI2 expression with TMB, MSI, tumor microenvironment, tumor- and immune-related genes, methyltransferases, and MMRs-related genes." (PMID 35552266, 2022). "We only found 5 DEGs (BIRP1, PARP1, RFC4, RMI2, and RAD51) had protein expression data in HPA and the results showed that the expression levels of BIRP1, PARP1, RFC4, RMI2, and RAD51 in BRCA tumor tissues were higher than in normal tissues." (PMID 34408776, 2021). "RMI2 expression was significantly correlated with satellite nodules (P = 0.024) and β-catenin expression (P = 0.043), but not with age, gender, tumor size, or differentiation." (PMID 37875822, 2023). "This study found that the expression of RMI2 was related to TME, immune infiltration, and ICPs of pan-cancer, but there are no in vivo or in vitro experiments directly proved that RMI2 affects the survival of tumor patients through these immunological mechanisms." (PMID 35552266, 2022).